PIGS (phosphatidylinositol glycan anchor biosynthesis class S)
Description:
Component of the glycosylphosphatidylinositol-anchor (GPI-anchor) transamidase (GPI-T) complex that catalyzes the formation of the linkage between a proprotein and a GPI-anchor and participates in GPI anchored protein biosynthesis.
Synonyms: PIG-S; DEE95; GPIBD18
Tractability: Small molecule: a structure with a bound ligand is known. Antibody: UniProt predicts a signal peptide or a membrane-spanning region. PROTAC: ubiquitination databases record sites on it; its protein half-life has been measured.
Gene: Protein-coding gene on chromosome 17 (28,553,383 to 28,571,794, reverse strand). Ensembl gene ENSG00000087111.
Subcellular location: Endoplasmic reticulum membrane
Pathways (Reactome):
Metabolism of proteins: Attachment of GPI anchor to uPAR
Gene Ontology:
Molecular function: protein binding
Biological process: attachment of GPI anchor to protein; GPI anchored protein biosynthesis; GPI anchor biosynthetic process
Cellular component: GPI-anchor transamidase complex; membrane; endoplasmic reticulum membrane
Genetic constraint (gnomAD): Loss-of-function variants: 33 observed, 58.03 expected, observed/expected ratio (o/e) 0.57, 90% interval 0.43 to 0.76. The upper end of that interval is the gene's LOEUF score, 0.76, which puts it in group 3 of 6, group 1 being the genes least tolerant of losing a copy. Missense variants: 625 observed, 743.69 expected, observed/expected ratio (o/e) 0.84, 90% interval 0.79 to 0.9. Synonymous variants: 269 observed, 304.98 expected, observed/expected ratio (o/e) 0.88, 90% interval 0.8 to 0.98.
Gene-disease validity (ClinGen):
ClinGen rates the evidence that PIGS causes each of these diseases.
glycosylphosphatidylinositol biosynthesis defect 18 (autosomal recessive): Definitive.
Homologues: Orthologues: chimpanzee PIGS (99% identical), macaque PIGS (97% identical), mouse Pigs (92% identical), pig PIGS (92% identical), guinea pig PIGS (91% identical), rat Pigs (91% identical), dog PIGS (90% identical), rabbit PIGS (84% identical), tropical clawed frog pigs (58% identical), zebrafish pigs (54% identical), Drosophila melanogaster PIG-S (26% identical), Caenorhabditis elegans pigs-1 (19% identical).
Diseases named in the same sentence as PIGS in open-access papers:
PIGS is named in the same sentence as 13 diseases in open-access papers, as found by Europe PMC text mining. Sharing a sentence is not in itself a finding about the gene and the disease. The quoted sentences say what the papers report.
developmental delay (1 paper, 2021). "Previous studies described seven patients with biallelic variants in the PIGS gene, of whom two presented with fetal akinesia and five with global developmental delay and epileptic developmental encephalopathy." (PMID 33410539, 2021).
enterovirus infection (1 paper, 2025). "To further characterize the role of PIGS or PIGK during enterovirus infection, we next employed EV71 subgenomic replicon systems (SGRs)." (PMID 41252368, 2025).
epilepsy (1 paper, 2021). A brain disorder characterized by episodes of abnormally increased neuronal discharge resulting in transient episodes of sensory or motor neurological dysfunction, or psychic dysfunction. "We confirm that biallelic variants in PIGS cause vitamin pyridoxine‐responsive epilepsy due to inherited GPI deficiency and expand the genotype and phenotype of PIGS‐related disorder." (PMID 33410539, 2021).
liver cancer (1 paper, 2020). An epithelial or non-epithelial malignant neoplasm that arises from the liver. "B4GALT2, B4GALT3, DPM1, DPM2, HS2ST1, and PIGS are unfavorable prognostic markers in liver cancer according to the analysis by human protein atlas." (PMID 32850363, 2020).
microcephaly (1 paper, 2023). A congenital or acquired developmental disorder in which the circumference of the head is smaller than normal for the person's age and sex. "Microcephaly has its highest prevalence in patients with PIGK and PIGS involvement, while PIGT mutated can be macrocephalic." (PMID 37510348, 2023).
Seizure (1 paper, 2023). A seizure is an intermittent abnormality of nervous system physiology characterized by a transient occurrence of signs and/or symptoms due to abnormal excessive or synchronous neuronal activity in the brain. "Seizures are very common in all the forms described, but they are more frequently controlled by medication in PIGK, GPAA1 and PIGU patients; seizures are often in-tractable, on the other hand, in the case of PIGS or PIGT variants." (PMID 37510348, 2023).
viral infection (1 paper, 2025). "We found that vRNA stability was significantly reduced in PIGS- or PIGK-KO cells, and 4μ8C partially rescued viral infection in PIGS- or PIGK-KO cells." (PMID 41252368, 2025).
tumour (3 papers, 2024 to 2026). "In fact, our analysis highlights not only the unique expression pattern of DaPs but also their interactions with PiGs in potentially regulating tumour progression." (PMID 38308202, 2024).
cancer (1 paper, 2021). A tumor composed of atypical neoplastic, often pleomorphic cells that invade other tissues. "PIGT, PIGU, GPAA1, and PIGS are overexpressed in many cancers, whereas PIGK is downregulated." (PMID 34193731, 2021).
infection (1 paper, 2025). The state of being infected such as from the introduction of a foreign agent such as serum, vaccine, antigenic substance or organism. "We next employed this CD55/TM molecule to evaluate the role of PIGS or PIGK during Echo7 infection." (PMID 41252368, 2025). "Similar to Echo7, infection of EV71 or CVB5 was significantly inhibited in PIGS- or PIGK-KO cells." (PMID 41252368, 2025). "PIGS- or PIGK-KO cells supplemented with CD55/TM were restored for CD55 expression, however, these cells still showed impaired infection and resistance to Echo7-induced cell death." (PMID 41252368, 2025).
PIGS also shares sentences with these, for which no sentence is quoted: dengue (1 paper); epileptic developmental encephalopathy (1); gastric cancer (1).